RELA (RELA proto-oncogene, NF-kB subunit)
Diseases named in the same sentence as RELA in open-access papers (continued):
Sharing a sentence is not in itself a finding about the gene and the disease.
metabolic disease (2 papers, 2019 to 2023). A congenital disorder (due to inherited enzyme abnormality) or acquired (due to failure of a metabolically important organ) disorder resulting from an abnormal metabolic process. "NF-kappaB, a transcription factor that has five subunits, namely p50, p52 RelA/p65, c-Rel and RelB, plays a critical role in inflammatory process and metabolic disease." (PMID 30926764, 2019). "Moreover, the DEGs regulated by NFκB1 and RELA were shown in two adipocytes that belong to the NF-κB family and play an important role in inflammation and metabolic disease." (PMID 37445596, 2023).
endocrine system diseases (1 paper, 2023). "Pirin, RELA (p65) and NFKBIA are significantly associated with endocrine system diseases." (PMID 38033031, 2023).
hematological cancers (1 paper, 2018). "While non-canonical NF-κB RELB signaling is described to be mostly present in hematological cancers, solid cancers reveal constitutive canonical NF-κB RELA or c-REL activity." (PMID 29673141, 2018).
psychiatric disorder (1 paper, 2016). A disorder characterized by behavioral and/or psychological abnormalities, often accompanied by physical symptoms. "The NF-κB family of transcription factors, including p50, p52, RelA/p65, cRel and RelB, have been shown to play important roles in hippocampal neurogenesis and psychiatric disorders." (PMID 27877109, 2016).
RELA also shares sentences with these, for which no sentence is quoted: CNS tumors (8 papers); lung adenocarcinoma (5); Cerebral ischemia (4); meningioma (4); esophageal cancer (3); esophageal squamous cell carcinoma (3); ganglioglioma (3); neuroepithelial tumor (3); osteopetrosis (3); pilocytic astrocytoma (3); renal fibrosis (3); respiratory diseases (3); acute erythroid leukemia (2); acute monocytic leukemia (2); allergic disease (2); cholera (2); ductal pancreatic adenocarcinoma (2); enterovirus infection (2); metastatic disease (2); nasopharyngeal carcinoma (2); oligodendroglioma (2); posterior fossa ependymoma (2); prion disease (2); stomach cancer (2); type II diabetes (2); Abdominal obesity (1); adenomyosis (1); allergic asthma (1); American trypanosomiasis (1); amyotrophic lateral sclerosis (1).
A further 95 diseases each share a sentence with RELA in 1 paper.